MDM2 (MDM2 proto-oncogene)
Diseases named in the same sentence as MDM2 in open-access papers (continued):
Sharing a sentence is not in itself a finding about the gene and the disease.
cancer (continued). "Consistent with the genetic data, PPM1D-dependent cancer cells also tended to be sensitive to pharmacologic inhibition of MDM2 using the MDM2 inhibitor Nutlin-3 (Pearson 0.38, P < 10−21)." (PMID 35105861, 2022). "Remarkably, Hinokiflavone inhibited MDM2 E3 ligase activity and caused the downregulation of MDM2 and MDMX in the tested cancer cell lines." (PMID 35625571, 2022). "Overall, these data showed that MDM2 inhibitor enhanced the antipancreatic cancer effects of USP22 overexpression in vitro and in vivo." (PMID 34743406, 2022). "Although MDM2 amplifications is common in many cancers, the role it plays in prognosis has been contradictory with some studies reporting favourable prognosis while others assert otherwise." (PMID 34695137, 2021). "Unfortunately, the increase in DSB repair efficiency in cancer cells with high MDM2 expression translates into clinical acquisition of a chemoresistant phenotype." (PMID 34572735, 2021). "This is even more interesting in light of the many MDM2 interacting proteins and implications for MDM2 antagonists as anti-cancer therapies, working synergistically with both chemotherapeutics and targeted therapies." (PMID 34769213, 2021).
cancer (continued). "Consistent with its role in these metabolic pathways, chromatin-bound MDM2 was shown to influence the redox status of both normal and cancer cells through the regulation of glutathione synthesis and recycling." (PMID 33406607, 2021). "Elevated MDM2 levels promote ubiquitination and degradation of E-cadherin, which in turn promotes cancer cell invasion." (PMID 34306137, 2021). "Such a 5- to 7-day high-dose pulse schedule was successfully adapted in multiple clinical trials to evaluate MDM2 inhibitors in cancer patients (clinicaltrails.gov)." (PMID 33941774, 2021). "Till date, cell cycle arrest and apoptosis have been reported as the primary mode of action of Artemisinin and its derivatives in cancer cells with Bax, Bcl2, caspase 3, cyclinB1, Cdc2 and Mdm2 as its popularly recognized targets." (PMID 34900697, 2021). "Genetic studies have linked other SNPs in the MDM2 and MDM4 genes to increased cancer incidence or premature aging." (PMID 33406607, 2021).
cancer (continued). "Upregulation of PD-L1 and CD276 by MDM2 inhibition results in antagonistic effects of this treatment by diminishing T-cell killing of cancer cells." (PMID 34911439, 2021). "The PPARγ agonist pioglitazone inhibited EGFR/MDM2 signaling-mediated PPARγ degradation and increased cancer cell sensitivity to chemotherapy drugs." (PMID 33935743, 2021). "Regarding the relationship between MDM2 protein and NSCLC tissues, MDM2 is highly expressed as a proto-oncogene in cancer tissues." (PMID 33612481, 2021). "Resistance to the inhibition of BCL2 was overcome by inhibiting MDM2; cancer cells can become resistant to BCL2 inhibition by increasing the production of other anti-apoptotic proteins, such as MCL-1." (PMID 35008180, 2021). "The E3, MDM2, promotes cancer stemness with an AR-negative signature in PCSCs by selectively degrading AR proteins." (PMID 34948357, 2021). "Within this context, targeting Bcl2 family attracted our interest given the evidence that inhibition of MDM2 and Bcl2 protein function synergistically induce apoptosis in cancer cells." (PMID 34970530, 2021). "Pharmacological targeting of MDM2 is currently under investigation with the aim of potentially sensitising cancer cells to topoisomerase inhibitors, a drug that induces R-loop formation." (PMID 34066546, 2021). "Despite the introduction of several efficient MDM2 inhibitors, various molecular mechanisms influencing cancer cell resistance to MDM2 inhibitors were reported." (PMID 34970530, 2021).
cancer (continued). "In summary, these findings suggest 6-TG and 6-MP reduce the stability of some USP2a targets, including FAS and Mdm2, by inhibiting USP2a-catalyzed deubiquitination in some cancer cells." (PMID 34956872, 2021). "MDM2 upregulation has been reported in various cancers, which renders it an attractive drug target for cancer therapy." (PMID 33805973, 2021). "Inhibition of MDM2 expression in the SKBR3 cell line (HER2 subtype) diminished the survival of cancer cells treated with doxorubicin, etoposide, and camptothecin." (PMID 34572735, 2021). "In cancer cells, MDM2 proteins help to modify biological programs, enhance growth-promoting signals, and reduce apoptotic signals." (PMID 34276798, 2021). "Further complexity has been recently added by Lozano’s group, who demonstrated that MDM2 SNP309G exhibits tissue-specific regulation and different impacts on cancer risk." (PMID 34307167, 2021). "MDM2 inhibitors, such as Nutlin-3a, suppress proliferation and promote apoptosis in OS and other cancers." (PMID 35049602, 2021). "CD4+ T cells that are reactive against a selected peptide from MDM2 have been developed and showed promising effects against cancer progression." (PMID 35071005, 2021). "We discuss that P14ARF (ARF) functions as a negative regulator of MDM2, explaining the frequent loss of ARF detected in cancers." (PMID 34065345, 2021). "Cancer cells with MDM2 amplification are selectively resistant to treatment with drugs introducing DSB (inhibitors of topoisomerase II)." (PMID 34572735, 2021).
cancer (continued). "The amplified DNA stretch corresponds to various cancer-related genes, the most studied being MDM2 (or HDM2 in humans) and CDK4, but also HMG2A, TSPAN31, YEATS4, and CPM." (PMID 34068344, 2021). "When tested in combination with nutlin-3, the expression of MDM2 in cancer cells was increased which in turn increases the anti-tumour response of the CD4+ T cells." (PMID 35071005, 2021). "This review covers the role of MDM2/X in cancer and more specifically in GB, followed by the rationale for the potential radiosensitizing effect of MDM2 inhibition." (PMID 34307171, 2021). "KRT-232 (AMG 232), a small-molecule inhibitor of MDM2, reduces IL-6 expression, enhances T-cell-mediated cancer cell killing, and exerts a strong antitumor effect." (PMID 34943817, 2021). "ECT2, which is deubiquitinated and stabilized by USP7, was found to enhance breast cancer cell proliferation in vitro and cancer growth in vivo by positively regulating the classical oncogenic signaling axis mediated by MDM2." (PMID 34575114, 2021). "Several studies observed the associations between single nucleotide polymorphisms (SNPs) in MDM2 and MDM4 genes and various cancers." (PMID 33669778, 2021). "MDM2 is often highly expressed in a variety of human cancers, and its overexpression promotes cancer cell's proliferation." (PMID 34306137, 2021). "Sirt6-induced cell death was substantially suppressed upon inhibition of MDM2, indicating that MDM2 plays an essential role in Sirt6-related cancer cell death." (PMID 33727672, 2021). "With our collaborators, we have recently identified several small molecule inhibitors that can simultaneously inhibit both NFAT1 and MDM2, and showed that these exert anticancer effects in vitro and in vivo against several models of cancer." (PMID 32397368, 2020). "This is significant because MDM2 is an important oncogene that plays a key role in the development and progression of various types of cancers." (PMID 32629830, 2020). "Targeting both NFAT1 and MDM2 using a single small molecule is a novel strategy to develop an effective targeted therapy for advanced cancer." (PMID 32397368, 2020).